STAT3 (signal transducer and activator of transcription 3)
Diseases named in the same sentence as STAT3 in open-access papers (continued):
Sharing a sentence is not in itself a finding about the gene and the disease.
hepatocellular carcinoma (continued). "Aberrant p-STAT3 expression has been identified in peripheral CD4+ and CD8+ T cells and related to development of hepatocellular carcinoma (HCC)." (PMID 37741983, 2023). "In hepatocellular carcinoma (HCC), TAMs facilitate the expansion of cancer cells by secreting IL-6 activating STAT3." (PMID 36260158, 2023). "STAT3 silencing using STAT3 ASO in HCCLM3, SNU423, and Huh7 hepatocellular carcinoma cells reduced cell proliferation, survival, and migration." (PMID 38067351, 2023). "Recent results further confirmed that α-GA inhibits STAT3 Tyr705 phosphorylation by increasing protein tyrosine phosphatase 1 and 2 expressions and inhibits TGF-β-triggered hepatocellular carcinoma invasion and metastasis in vivo and in vitro." (PMID 35967372, 2022). "Evidence obtained from studies on hepatocellular carcinoma (HCC) revealed a possible inter-connection between C/EBPβ and STAT3 in the context of MDSC expansion." (PMID 35158779, 2022). "In hepatocellular carcinoma, the replenishment of miR-486-5p blocks the IGF-1R pathway by acting on the downstream mediators such as mTOR, STAT3, and c-myc." (PMID 35337095, 2022). "It is necessary to elucidate the target of CDCA as a target drug carrier for hepatocellular carcinoma, and this paper verified that CDCA is enhancing the therapeutic effect of sorafenib on hepatocellular carcinoma through EGFR/Stat3 pathway." (PMID 35252007, 2022). "In hepatocellular carcinoma, circ-LRIG3 enhances EZH2 expression and induces STAT3 methylation to promote cancer progression." (PMID 35236381, 2022). "In another study, synergistic anti-tumor effects of artesunate and sorafenib were detected against hepatocellular carcinoma cells (PLC/PRF/5, HuH7, HepG2, Hep3B and HCCLM3) through targeting the ERK pathway and STAT3." (PMID 35267408, 2022). "Silencing DJ-1 in human hepatocellular carcinoma cells (HCCs) induces PTEN expression as well as inhibition of interleukin (IL)-6/Signal Transducer and Activator of Transcription 3 (STAT3), MAPK and AKT, resulting in reduced cell proliferation." (PMID 35563738, 2022). "In hepatocellular carcinoma, FYN-mediated activation of the STAT3 pathway plays an important role in Fzd2-driven EMT and the migration of liver cancer cells." (PMID 36498797, 2022). "STAT3 signalling pathway correlates with the EMT process and stemness in oral squamous cell carcinoma and hepatocellular carcinoma." (PMID 36372977, 2022). "STAT3 gene is highly expressed in hepatocellular carcinoma cells, and regorafenib (Stivarga), a drug targeting STAT2 for the treatment of hepatocellular carcinoma, has been identified as a second-line oral agent." (PMID 35927985, 2022). "PRPF3 was reported to be a potential prognostic indicator in hepatocellular carcinoma and promoted the cell growth, migration, and invasion of keratinocyte-derived cutaneous squamous cell carcinoma via the JAK2/STAT3 pathway." (PMID 35260078, 2022). "In hepatocellular carcinoma, miRNA-137 inhibits migration and metastasis via targeting EZH2/STAT3 signaling." (PMID 35236381, 2022). "Our previous studies performed in human hepatocellular carcinoma (HCC) cell lines, provided evidence that PN is able to sensitize TRAIL-induced apoptosis by reducing phosphorylated STAT-3 levels." (PMID 35203723, 2022). "However, the involvement of constitutive STAT3 activation is common in tumors, including in the case of hepatocellular carcinoma (HCC)." (PMID 36080130, 2022). "AFP can activate the PI3K/AKT signalling, stimulates the transcription cofactor mTOR, STAT3, HIF‐1α and Bcl‐2, which regulates the expression of oncogenes, as well as promotes angiogenesis and the growth of the hepatoma cells." (PMID 36181321, 2022). "Inhibition of the JAK2/STAT3 pathway induced by ANGPTL1 represses angiogenesis and metastasis in hepatocellular carcinoma." (PMID 35980290, 2022).
hepatocellular carcinoma (continued). "In hepatocellular carcinoma, lncRNA TINCR interacts directly with and inhibits PTPN2 to promote the proliferation and invasion through activating STAT3 signaling." (PMID 35957898, 2022). "For example, in hepatocellular carcinoma, TLR9 agonist treatment decreased PARylation of STAT3 and expression of PARP-1." (PMID 36077221, 2022). "Besides, in bufothionine-treated SMMC-7721 hepatocellular carcinoma cells, it could be observed that the concentration of IL-6 was decreased, the expression of p-Stat3-tyr705, p-Stat3ser727, and JAK2 was downregulated, as well as there was an increase in Atg5, Atg7, and LC3-II." (PMID 36104717, 2022). "NCAPG2 overexpression drives Hepatocellular carcinoma (HCC) proliferation and metastasis by activating the STAT3 and NF-κB/miR-188-3p pathways." (PMID 36139554, 2022). "STX12 was upregulated through the ROS/STAT3/NFE2L1 axis in hepatoma cells, and it was a key downstream effector of NFE2L1 in modulating hepatoma cell invasiveness." (PMID 36400805, 2022). "In colon cancer and hepatocellular carcinoma cells, FPR1 elicits signaling pathways related to chronic inflammation that activate ERK, MAPK and the transcriptional factors, NF-kB and the signal transducer and activator of transcription 3 (STAT3)." (PMID 34571894, 2021). "In the cytoplasm of hepatocellular carcinoma cells, LncRNA00364, which is upregulated by IFN-γ can directly interact with STAT3 and then inhibit the phosphorylation of tyrosine-705 of STAT3 to function as a tumour suppressor." (PMID 34425834, 2021). "In hepatocellular carcinoma, human CAFs can attract monocytes by the SDF-1a/CXCR4 pathway and facilitate their differentiation into MDSCs via IL-6-mediated STAT3 activation." (PMID 34336660, 2021). "In hepatocellular carcinoma, miR-515-5p inhibits the invasion and migration of cancer cells by suppressing the IL6/JAK/STAT3 pathway." (PMID 33539322, 2021). "Ilexgenin A has been shown to repress melanoma via inducing cell cycle arrest and exerting anti-hepatocellular carcinoma activity by inhibiting the PI3K and STAT3 pathways." (PMID 34575983, 2021). "In hepatocellular carcinoma cells, a cross-talk between DDR1 and STAT3 enhances tumor progression by promoting proliferation, migration and invasion in vitro, and tumorigenesis in vivo." (PMID 33917302, 2021). "In HBV-related hepatocellular carcinoma, lncRNA activates HBV through regulating HBx/STAT3/miR-539/APOBEC3B axis, thereby promoting the progression of HBV-related hepatocellular carcinoma." (PMID 34104647, 2021). "Our results demonstrated that cryptolepine inhibits the IL-6/STAT3 signalling pathway, and therefore cryptolepine-based remedies such as Cryptolepis sanguinolenta could potentially be used as an effective immunotherapeutic agent for hepatocellular carcinoma and other cancers." (PMID 34078370, 2021). "The inhibition of the STAT3 and MMP2/MMP9 signaling pathway reversed EMT and inhibited the migration and invasion of hepatocellular carcinoma cells." (PMID 34876128, 2021). "For example, knockdown of eEF2K was found to prevent tumor progression and angiogenesis of hepatocellular carcinoma via the PI3K/Akt and STAT3 signaling pathway." (PMID 33673713, 2021). "By reducing STAT3 and HIF-1α levels, sulforaphane also diminishes VEGF expression, exerting anti-angiogenic effects in hepatocellular carcinoma." (PMID 34575983, 2021). "Bicuculline can effectively inhibit the migration and invasion of human hepatocellular carcinoma MHCC97-H cells which is related to the downregulation of VEGF, MMP-2, and MMP-9 gene expression and inhibition of JAK2/STAT3 signaling pathway activation." (PMID 34497656, 2021). "STAT3 has also been shown to be activated by phosphorylation in both Ser and Tyr residues in HCV NS5A‐transiently transfected hepatoma cells, as well as in the liver of NS5A transgenic mice." (PMID 33247551, 2021).
hepatocellular carcinoma (continued). "In hepatocellular carcinoma (HCC), miR-340 inhibits cell proliferation and tumor growth by inhibiting SKP2 expression 47, and regulating the JAK1/STAT3 pathway." (PMID 33390846, 2021). "Additionally, elevated tight junction proteins claudin-9 and claudin-17 stimulate migration and invasion of hepatocellular carcinoma (HCC) (liver cancer) cells through activation of the TYK2/STAT3 pathway." (PMID 34439323, 2021). "In hepatocellular carcinoma, α-SMA+ CAFs are found to produce IL-6 for recruiting neutrophils via the activation of STAT3 and c-Jun kinase-programmed cell death ligand 1 (STAT3-PDL1)." (PMID 33540679, 2021). "We further demonstrated that STX12 is upregulated through the ROS/STAT3/NFE2L1 axis and is a key downstream effector of NFE2L1 in modulating hepatoma cell invasiveness." (PMID 32942643, 2020). "More recently, IL-6/JAK1-mediated STAT3 phosphorylation was found to promote the transcription of DNMT3B and OCT4 in hepatocellular carcinoma cells, which can further up-regulate the transcription of DNMT156." (PMID 32895373, 2020). "Consistent with our study, the activation of STAT3 by RPN2 was found in other types of cancers, including colon carcinoma, hepatocellular carcinoma." (PMID 32404045, 2020). "STAT family of genes, particularly the STAT3 pathway, is also modulated by garcinol for its apoptotic activities and, the observation has also been correlated in xenografted tumor of hepatocellular carcinoma (HCC)." (PMID 32365899, 2020). "The ligation of IL-22R1/IL-10R2 phosphorylates JAK1 and TYK2, and activates mainly STAT3 in keratinocytes, and STAT3, to a lesser extent, STAT1 and STAT5 in hepatoma cell lines." (PMID 32751111, 2020). "Furthermore, in hepatocellular carcinoma (HCC), CAFs secrete high levels of IL-6, which promoted stem cell-like properties in HCC cells by activating Notch 1 signalling through STAT3 Tyr705 phosphorylation." (PMID 32575680, 2020). "For example, lncRNA TSLNC8 acts as a tumor suppressor in hepatocellular carcinoma and exerts its effects through the JAK/STAT3 pathway." (PMID 32983994, 2020). "In a co-culture of hepatocellular carcinoma (HCC) cells and macrophages, IL-6/STAT3 signaling pathway was suppressed in M1 macrophages but was activated in M2 macrophages." (PMID 32486098, 2020). "Quercetin inhibited hepatocellular carcinoma progression by modulating cell apoptosis, migration, invasion, and autophagy; and its effects were at least partly related with the JAK2/STAT3 signaling pathway." (PMID 31273958, 2019). "STAT3 protein together with IL6, HNF4A, HNF1A, and three microRNAs constructed a feedback loop, which regulates oncogenesis of hepatocellular carcinoma (HCC)." (PMID 31219249, 2019). "Importantly, this pathway may not be specific to pancreatic cancer: CAFs isolated from human hepatocellular carcinomas were capable of driving an immunosuppressive gene signature and functions in monocytes and in neutrophils via IL-6 mediated activation of STAT3 signaling." (PMID 31428105, 2019). "Constitutively activated STAT3 plays a pivotal role in holding cancer stemness of HCC CSCs, which are essential for hepatoma initiation, relapse, metastasis and drug resistance." (PMID 30709346, 2019). "A recent study found that after treatment of hepatocellular carcinoma cells with melatonin, HCC-derived exosomes can alter the immunosuppressive status through the STAT3 pathway in macrophages." (PMID 31142326, 2019). "STAT3 is constitutively activated in human hepatocellular carcinoma (HCC) cells, and the inhibition of STAT3 signaling pathway affects cell growth and induces cell apoptosis of HCC cells." (PMID 30709346, 2019). "In hepatoma cells, phosphorylated STAT3 was also found to bind to the SNAI1 promoter; inhibition of STAT3 abrogated the hepatitis virus C core-induced Snail1 expression." (PMID 31141910, 2019).
hepatocellular carcinoma (continued). "Human hepatoma Huh-7 cells transfected with an NS5A vector have demonstrated an elevation of ROS with resulting activation of NF-KB and STAT-3 pathways that then led to the release of various array of cytokines, including IL-6, IL-8, TNFα, and TGFβ." (PMID 31540136, 2019). "Via CSF1‐R and CD138, IL‐34 promoted the proliferation and migration of hepatoma cells, and contributed to the activation of ERK and STAT3 pathways and the upregulation of Bcl‐xl and c‐Myc mediated by HBX." (PMID 31621133, 2019). "STAT3-targeting ODNs significantly decrease HBV RNA expression and DNA replication in hepatoma cell lines." (PMID 29543893, 2018). "At the post-receptor level, prolonged treatment with insulin is known to inhibit JAK2/STATs signaling by reducing JAK2 and STAT5 phosphorylation and protein content of STAT3, e.g., in H4IIE hepatoma cells." (PMID 29977227, 2018). "In HuH7, a human hepatoma cell line, leptin treatment resulted in increased HAMP mRNA, which was regulated by the JAK2/STAT3 signaling cascade." (PMID 30360386, 2018). "However, when liver injury persists, as in the case of chronic viral hepatitis, liver inflammation paired with constant STAT3 activity fosters the development of hepatocellular carcinoma (HCC)." (PMID 29543893, 2018). "Ke found that scutellarin could inhibit hepatocellular carcinoma (HCC) cell metastasis in vivo, and migration and invasion in vitro by downregulating the STAT3/Girdin/Akt signaling." (PMID 28635646, 2017). "TGF-β1 and IL-6 are predominantly produced by TAMs in hepatocellular carcinoma (HCC), which induce EMT and activate the STAT3 pathway, respectively, to promote liver CSC properties." (PMID 28337221, 2017). "Methylation silencing of SOCS3 increases the IL-6/JAK/STAT3 and FAK phosphorylation in human hepatocellular carcinoma." (PMID 28228755, 2017). "Cell surface GRP78 directly bound to and phosphorylated c-src for EGFR activation, promoting the invasion and metastasis of hepatocellular carcinoma (HCC) cells, and accelerating the proliferation and migration of breast cancer cells by activating STAT3." (PMID 29069845, 2017). "Based on our previous finding that OSM mediates HIF-1 α upregulation through increased mRNA and protein levels in a STAT3-dependent manner, we aimed to investigate the effects of OSM stimulation on central carbon metabolism in hepatocytes and hepatoma cells." (PMID 26889381, 2016). "By using a murine in situ hepatoma model, we further demonstrated that MIF contributes to anti-hepatoma activity of ConA by regulating STAT3–MIF–BNIP3-dependent autophagy." (PMID 26633714, 2015). "The combination of cisplatin with YC-1, which promotes STAT3 degradation and reduces HIF-1α protein levels, results in enhanced sensitivity of hepatocellular carcinoma cells to cisplatin and suppression of tumor growth." (PMID 26106584, 2015). "The signal transducer and activator of transcription 3 (STAT3) pathway has been shown to be required for self-renewal of TICs in several types of cancers, including hepatoma and glioblastoma." (PMID 24424445, 2014). "The proposed results are significant, as the relative ratio of STAT3 and SHP-1 has been shown to be critical in T cell breast lymphoma and Hepatocellular Carcinoma pathologies." (PMID 25333362, 2014). "Constitutive activation of signal transducer and activator of transcription 3 (STAT3) has been linked with proliferation, survival, invasion and angiogenesis of a variety of human cancer cells, including hepatocellular carcinoma (HCC)." (PMID 24655440, 2014). "It was seen that STAT3 forms a complex with c-Fos and c-Jun to bind and up regulate the ICAM1 gene in HepG2 human hepatocellular carcinoma cells." (PMID 24743777, 2014). "In hepatocellular carcinoma, EGCG lowers the expression of phosphorylated STAT3 protein and inhibits the expression of multiple genes including Bcl-xL." (PMID 25270015, 2014).
hepatocellular carcinoma (continued). "In hepatocellular cancer, miR-21 was predicted to regulate “immune response” by targeting CD69, STAT3, CCL20 and SMAD7, in which STAT3 and SMAD7 are important signaling molecules for immune response." (PMID 24278370, 2013). "STAT3 is constitutively activated in HCC tissues and hepatoma cell lines through several mechanisms." (PMID 24213315, 2012). "Hence, inhibition of HIF-1α and STAT3 could prove valuable for therapy of hepatocellular carcinoma." (PMID 18651980, 2008). "The present study shows that the 2ME2-analog ENMD-1198 interferes with growth factor-induced signaling in hepatocellular carcinoma and effectively inhibits HIF-1α and STAT3 activation." (PMID 18651980, 2008). "Moreover, IL-6 not only stimulates the Janus kinase (JAK)-signal transducer and activator of transcription 3 (STAT3) pathway, but also promotes the steps leading up to the development of hepatocellular carcinoma." (PMID 39944822, 2025). "Similarly, in hepatocellular carcinoma, HSF1 has been reported to upregulate PD-L1 expression by inducing APOJ expression and activating the STAT3 signaling pathway." (PMID 40675964, 2025). "Hepatocellular carcinoma (HCC) is another inflammation-driven cancer, where inflammatory cytokines such as TNF-α and IL-6 activate downstream targets including NF-κB, JNK, and STAT3, thereby promoting tumorigenesis." (PMID 40051564, 2025). "Similarly, in later years, it was demonstrated that in hepatocellular carcinoma (HCC), AChE activated the STAT3 and AKT pathways by interacting with the androgen receptor (AR), enhancing the migration and invasion of HCC cells while inhibiting their apoptosis." (PMID 40678419, 2025). "In addition, miR-29c expression is downregulated in human hepatocellular carcinoma (Huh7) cells infected with HCV JFH-1 strain, accompanied by upregulated STAT3 mRNA and protein levels." (PMID 41488475, 2025). "In addition, brevilin A inhibited the Stat3/Snail and Wnt/β-catenin signalling pathways in HCC cells, which led to the inhibition of hepatocellular carcinoma." (PMID 41157091, 2025). "In hepatocellular carcinoma, FMRP accelerates the metastasis of cancer cells by binding to the 3′ UTR of STAT3 mRNA, enabling its localization to cellular protrusions and the subsequent activation of STAT3 translation." (PMID 40271197, 2025). "For instance, STAT3 could specifically promote the transcription of lncRNA HOXD-AS1 and prevented the degradation of SOX4, thus promoting the metastasis of hepatocellular carcinoma (HCC)." (PMID 41208976, 2025). "HBx protein was reported to be able to upregulate STAT3 and p-STAT3 levels by promoting the transcriptional activity of long non-coding RNAs in a nude mouse model of hepatocellular carcinoma." (PMID 38444939, 2024). "Furthermore, it was demonstrated that administering CuI to HepG2 hepatocellular carcinoma cells decreases the number of proteins in the PI3K/AKT/mTOR, MAPK, and JAK2/STAT3 cascades." (PMID 38397437, 2024). "Moreover, STAT3 signaling promotes EMT in colorectal cancer, hepatocellular carcinoma, and prostate cancer." (PMID 38720012, 2024). "HIF-1α, STAT3, and VEGF signaling molecules interact and form the HIF-1α/STAT3/VEGF signal transduction pathway, which probably plays an important role in the occurrence and development of hepatocellular carcinoma." (PMID 37333486, 2023). "For example, when TAMs are cocultured with hepatoma cells, macrophage-derived IL-6 and IL-8 activate JAK kinase, which phosphorylates STAT3 activating STAT3 signaling in tumor cells and promotes the epithelial mesenchymal transition(EMT), thus enhancing tumor invasion and metastasis." (PMID 36816959, 2023). "Unlike PSC, immunohistochemistry did not reveal phospho-STAT3 expression in the nontumor-bearing tissue obtained from hepatic resections of hepatocellular carcinoma representing apparently normal liver histology or hepatic steatosis only." (PMID 37256725, 2023).